CXCL1 (C-X-C motif chemokine ligand 1)
Diseases named in the same sentence as CXCL1 in open-access papers (continued):
Sharing a sentence is not in itself a finding about the gene and the disease.
infection (continued). "The fact that CXCL1 and CCL2 peaked early on the infection when blood RSV RNA was detected at very low levels, and inversely correlated with the peak of RSV RNA loads on day 4 may reflect the different dynamics of viral replication and cytokine production in RSV disease." (PMID 20843364, 2010). "Thus, the elevated CXCL1 we observed in Ctsz−/− lungs may be driven by macrophages, especially during the early stages of infection, and appears to be independent of mycobacterial pathogenicity." (PMID 40924769, 2025). "Additionally, our results revealed several mechanisms, which may serve to compensate for the impaired effector functions of PMN in CD18Ly6G cKO mice upon infection: Particularly, we could observe a higher level of the PMN-attracting chemokine CXCL-1 in BALF obtained from CD18Ly6G cKO mice." (PMID 35734179, 2022). "Similarly, CXCL1 and CXCL2 quickly increased in the early stages of GBS infection, while a significant difference in these two factors in WT and Fpr2-/- can be detected at 1 hour and 3 hours for both i.v. and i.p. infection route, which is consistent with that of the neutrophils increase." (PMID 34899755, 2021). "Moreover, we did not observe increased expression of CXCL1, one of the chemokines known to recruit neutrophils to the lamina propria soon after infection, in Citrobacter dosed animals regardless of the diet, suggesting that IL-22 was upregulated via a different pathway." (PMID 32082288, 2020). "Furthermore, SARS-CoV-2 D614G[Omicron spike] infection resulted in a significantly increased expression of ISGs Mx1, Oas1, and Viperin as well as Cxcl10, while pro-inflammatory mediators Cxcl1, Ccl2, and Il6 were not significantly altered in any group compared to the uninfected mice." (PMID 38742107, 2024). "In contrast, the apical CXCL1 and CXCL8 concentrations decreased sharply from the baseline in the presence of live parasites (“fit” and “non-fit” infections)." (PMID 37141303, 2023). "We thus identified several alternative inflammatory genes whose expression was either completely (Cxcl1) or partially (Ccl2 and Il6) independent of IFNAR1 signaling following infection." (PMID 38011306, 2023). "MGSA/CXCL1 acts as a chemoattractant for neutrophils or other non-hematopoietic cells, recruiting them to the site of damage or infection, and plays an important role in the regulation of immune and inflammatory reactions." (PMID 36293292, 2022). "T. denticola single species implant infections systemically increased IL-6, IL-13, CXCL1/KC, CCL-3/MIP1α, and CCL2/MCP compared to tissue infection without the implant." (PMID 35203495, 2022). "S. oralis infections as single species caused a significant increase in the expression of IL-1α, IL-6, IL-12 (p40), CXCL1/KC, CCL5/RANTES, and CCL11 compared to infection without implants." (PMID 35203495, 2022). "IL-1β, TNF-α, CXCL1, and CXCL2 were significantly decreased in fibrotic mice compared with nonfibrotic mice after infection, both at the protein and mRNA levels." (PMID 34990413, 2022). "At early time points, Fpr2-/- mice showed a significant decrease in CXCL1, CXCL2, IL-1β, CCL2, GM-CSF, IL-6, and CCL3 levels at 1 hour and 3 hours after infection, and an increase in IL-22 and IL-23, but there is no change in TNF-α, as compared with WT mice." (PMID 34899755, 2021). "TNF-α, IL-6, CXCL1, CCL2, and CCL7 levels significantly increased in the sera of klotho WT and KO mice at 1 day post-infection, while the level of IL-12 was not." (PMID 33329595, 2020). "histolytica infection, TNF and CXCL1, but not CCL2, were produced by Ly6Chi monocytes with a clear bias towards males." (PMID 32651360, 2020). "Plasma levels of the homeostatic chemokine CXCL12, neutrophil-targeted CXCL1, eosinophil-targeted CCL11 and the memory T cell-homing chemokine CCL27 remained high during infection and were not differentially regulated based on the severity of disease." (PMID 33613280, 2020).
infection (continued). "In contrast, we observed significantly enhanced expression of Cxcl1 (KC), Il6, and Il17, but not of Cxcl2 (MIP-2), Ifng, or Il10, in the huLangerin group as opposed to WT controls after infection with the S. aureus ΔtarM mutant." (PMID 31088921, 2019). "There were minimal levels of serum IL-6, CCL2, CXCL1, and TNF-α in mice without CVB3 infection, while those infected with CVB3 had significantly increased inflammatory cytokines and chemokines on day 5 post infection, which might be associated with exacerbation of pancreatic inflammation." (PMID 27195463, 2016). "We found that macrophages from gp91phox−/− and WT mice produced similar levels of IL-6, TNF-α, IL-17A and CXCL-1, MCP-1 and IL-10, regardless of infection with L. amazonensis." (PMID 27056545, 2016). "When mice were depleted of neutrophils at 8 weeks post-infection and evaluated at 12 weeks post-infection, they showed significant decrease in levels of CCL3 (MIP-1α), CCL4 (MIP-1β), CXCL1 (KC), LIF, G-CSF and M-CSF (Data not shown)." (PMID 27690127, 2016). "CXCL1 and CCL2 expression after infection with UV-inactivated virus was not statistically different from that with intact virus." (PMID 20419141, 2010). "However, serum and tissue levels of CXCL1/KC and IL-6 were elevated during infection, and both AZD5148 and bezlotoxumab were effective in lowering CXCL1/KC and IL-6 levels in sera (p < 0.0001), but not in tissue." (PMID 41183070, 2025). "CXCL1 is a CXC family member that acts as a key chemoattractant for immune cells, especially neutrophils and other non-hematopoietic cells to sites of injury or infection and plays a key role in the regulation of immune and inflammatory responses." (PMID 37237543, 2023). "Moreover, the secretion of neutrophil chemoattractants, CXCL1 and CXCL5, were significantly induced after 6- and 10-weeks post-infection in the absence of Lyl1." (PMID 36119114, 2022). "However, therapeutic treatment with Ac2–26, given as a single dose at 24 h post-infection, was not sufficient to decrease MPO, CXCL1, or IL-6 levels in mice compared with untreated WT (BALB/c) animals." (PMID 36078125, 2022). "However, there were no HIF-1α-dependent differences in lung cytokine secretion, indicating that lung epithelial HIF-1α is not required to induce IL-1β, IL-6, CXCL1, CXCL2, or MIP-3α secretion during infection." (PMID 27624128, 2016). "While IL-17R KO animals predictably had significantly higher amounts of IL-17 in brain abscess homogenates, several other mediators were also elevated between 7 and 14 days after infection, including IL-1α, IL-1β, IL-6, CCL3 and CXCL1 (data not shown), as well as CXCL2 and CXCL9." (PMID 22704602, 2012). "In the mutant strain infection, we noted that Th17-related cytokines (IL-17A, IL-22) and neutrophil-related chemokines (CCL2, CCL3, CXCL1, CXCL2) are significantly reduced at the early stage of infection, which might be related to the absence of melanin and defects in growth and germination." (PMID 35696422, 2022). "Importantly, whereas flagellin was not required for the role of Dnmt3b in Pseudomonas induced CXCL1 expression in BEAS-2B cells in vitro, Dnmt3bfl/flCc10Cre mice only demonstrated an enhanced innate immune response after infection with WT PAK but not after infection with flagellin deficient PAKflic." (PMID 33793661, 2021). "When injected 30 min prior to HAdV-D37 infection, PP2 reduced corneal inflammation as assessed by histology 4 days post infection and also reduced CXCL1 expression by ELISA at 16 hr post infection (p<.05), while the PP2 solvent DMSO alone did not reduce inflammation or CXCL1 expression." (PMID 24147000, 2013). "More precisely, P2Y2−/− mice presented increased levels of KC/CXCL-1 and MIP-2/CXCL-2 chemokines in their BALFs, but no significant higher infiltration of neutrophils or macrophages was observed in the inflamed lungs of P2Y2−/− mice until day 10 post-infection." (PMID 23185614, 2012).
cancer (509 papers, 2007 to 2026). A tumor composed of atypical neoplastic, often pleomorphic cells that invade other tissues. "Although it has been found that CXCL1 secreted by cancer-associated fibroblasts led to increased ROS burst, the underlying molecular mechanisms and their effect on mitochondrial activity are awaiting to be explored." (PMID 41255573, 2025). "Previous reports highlighted stimulation of interleukin‐6 (IL‐6), interleukin‐8 (IL‐8), and growth‐regulated alpha protein (CXCL1) production by keratinocyte‐conditioned medium in fibroblast cells and implicated these cytokines in cancer." (PMID 40621923, 2025). "Intriguingly, macrophage infiltration and the high level of CXCL1 were also enriched in cancer-associated adipocyte tissues, accompanied by an increased number of CLS." (PMID 41255573, 2025). "Recent research evidence shows that the high expression level of CXCL1 in different types of cancers is associated with advanced cancer stage, larger cancer volume, cancer invasiveness, and poor prognosis." (PMID 40527884, 2025). "The role of CXCL1 in cancer processes can be divided into its influence on cancer cells and cancer-associated cells." (PMID 38673949, 2024). "PCCs are shown to produce excess chemokines that are heavily involved in the activation of Cancer-associated fibroblasts, including CXCL1, -5, and -8 binding to fibroblasts’ CXCR2 receptors, leading to increased fibroblast activation and reprogramming." (PMID 38361931, 2024). "CXCL1 causes the proliferation of MM cells and is pro-angiogenic; for this reason, CXCL1 levels in the blood of patients with this cancer are correlated with bone marrow microvascular density." (PMID 38673949, 2024). "A strong association between CXCL1 and cancer chemoresistance was also supported by numerous studies." (PMID 39394189, 2024). "CXCL1 also causes the migration of the cancer cells of the cancer in question —this effect depends on ERK MAPK activation." (PMID 37108425, 2023). "CXCL1 increases the proliferation of OSCC cancer cells, which is associated with the activation of CXCR2 that transactivates epidermal growth factor receptor (EGFR)." (PMID 37408240, 2023). "Studies on mice indicate that CXCL1 can affect HCC cancer stem cells, as CXCR2 ligands cause quiescence of these cells." (PMID 37408240, 2023). "Extensive research has been conducted on the role of cancer-associated fibroblasts (CAFs) in solid tumors, particularly in relation to their production of soluble factors such as IL-1α, IL-1β, CXCL1, CXCL12, G-CSF, and IL-6." (PMID 37880682, 2023). "IHC staining of Ki67 suggested that loss of the Phgdh/cMyc axis or the neutralization of Cxcl1 and Il8 hampered cancer cell proliferation in the liver." (PMID 37078828, 2023). "For instance, CXCL1 has been linked to the promotion of cancer cell migration and the progression of gastric cancer and breast cancer metastasis." (PMID 36969851, 2023). "It has been observed that carboplatin increases CXCL1 expression in cancer-associated MSC, resulting in increased resistance to subsequent cycles of chemotherapy." (PMID 37108425, 2023). "Because CXCL1 is an angiogenic chemokine, Notch signaling in cancer increases CXCL1 expression, and thus causes angiogenesis." (PMID 35054978, 2022). "CXCL1 is implicated in angiogenesis, inflammation, wound healing, and cancer, as well as blocking the oligodendrocyte precursor's migration in the spinal cord." (PMID 35958781, 2022). "It has been reported that CXCL1-mediated interaction of cancer cells with TAMs and cancer-associated fibroblasts (CAFs) promotes tumor progression in BC." (PMID 35607322, 2022). "TNF-α upregulated the expression of CXCL1/2 in cancer cells through the NF-κB signaling pathway, thereby amplifying the CXCL1/2-S100A8/9 loop and causing chemoresistance." (PMID 34813418, 2022). "Studies have demonstrated high expression of CXCL1 in a variety of cancers and its association with cancer progression and inflammation." (PMID 36434686, 2022).
cancer (continued). "In terms of diagnostic value, the mRNA expression of CXCL1 in COAD cancer tissues is significantly higher than that in adjacent normal colon tissues, and ROC data show that CXCL1 does not significantly affect the prognosis of COAD." (PMID 35958781, 2022). "As research goes on, CXCL1 has been identified to be intimately associated with the development of various cancers." (PMID 34079750, 2020). "IL-6 is a critical pleiotropic cytokine associated with innate immunity and cancer; it is known to inhibit expression of CXCL1, and is a prominent target for clinical intervention." (PMID 31114758, 2019). "CXCL1 is implicated in tumorigenesis, angiogenesis, invasion, metastasis and resistance to several anti-cancer chemotherapies." (PMID 29662619, 2018). "High CXCL1 expression was associated with advanced cancer stage, lymph node (LN) metastasis and poor survival." (PMID 30158589, 2018). "IL-6, IL-8, CXCL1, GM-CSF, and TGFβ2 are recognized pro-tumorigenic factors associated with cancer progression." (PMID 30111846, 2018). "TNF-α can heighten the expression of CXCL1/2 in cancer cells, thus amplifying the CXCL1/2-S100A8/9 loop and causing chemo-resistance." (PMID 29245915, 2017). "Taken the consistent results, the present results demonstrated that the activation of EGFR was positively associated with the induction of cancer chemokines (IL-8 and CXCL-1) via NF-κB-independent pathways in type I EOC cells." (PMID 27708225, 2016). "The MB-downregulated genes include cancer-associated cytokines/chemokines (e.g. CXCL1, CXCL2, CXCL3, CXCL14, IL1A, IL1B, IL6, IL8) and matrix metalloproteinases (MMP1,MMP9)." (PMID 25642713, 2015). "Among the cytokine related pathways, high expression of VEGF, CXCL8, CXCR2, and CXCL1 are associated with cancer metastasis and progression." (PMID 22479608, 2012). "Based on these findings, we hypothesize that FOXI1 and CFTR are not only major regulators of lung ionocytes but also closely associate with CXCL1 cancer subpopulations." (PMID 40568194, 2025). "Although CXCL1 is virtually undetectable at baseline, its expression increases under pathological conditions, and abnormal expression of CXCL1 is often associated with the development of certain cancers." (PMID 36614235, 2023). "CXCL1 expression is also upregulated by LIF secreted by cancer-associated adipocytes." (PMID 37108425, 2023). "Additionally, we present the impact of CXCL1 on the microenvironment of reproductive cancers, including its effect on angiogenesis, recruitment, and function of cancer-associated cells (macrophages, neutrophils, MDSC, and Treg)." (PMID 37108425, 2023). "Through these cells, CXCL1 causes angiogenesis and cancer-immune evasion." (PMID 37108425, 2023). "As this cancer is associated with inflammation, one of the components of its pathogenesis is CXCL1." (PMID 37408240, 2023). "Additionally, CXCL8 also enhances cancers by controlling stem cell mass, and CXCL1 is associated with the occurrence of drug resistance." (PMID 36431173, 2022). "Finally, CXCL1 alone can also cause senescence, which has important implications in malignant tumors." (PMID 35457023, 2022). "Due to its secretory phenotype, we speculate that iCAF induced by CXCL1 may be involved in cancer‐associated systemic effects." (PMID 34218518, 2021). "IL‐6, CXCL1 and TGFβ2 are known pro‐tumorigenic factors associated with cancer progression." (PMID 34216174, 2021). "Transcript levels of soluble factors often linked to cancer-promoting (CP) inflammation, such as IL-6, CXCL1, CXCL2, IL-1β, or G-CSF, were markedly higher in COX-competent compared to COX-deficient tumors, and their expression was unchanged in the absence of NK cells." (PMID 33220234, 2020). "In addition to cancer cells, CXCL1 caused endothelial cell proliferation, tube formation, and migration." (PMID 24376747, 2013). "In addition to cancer cells, cancer-associated fibroblast (CAF) also produces CXCL1 in OSCC." (PMID 37408240, 2023).
cancer (continued). "In addition, the molecular mechanisms underlying the promotion of cancer metastasis by CXCL1 are also unknown." (PMID 30158589, 2018). "As our findings showed that Vox strongly reduced neutrophils in tumors, we analyzed the expression of Cxcl1, Cxcl2 and Cxcl5 (genes encoding neutrophil-recruiting chemokines) in FACS-sorted cancer cells, total immune cells, neutrophils and macrophages." (PMID 40139833, 2025). "Recent research has demonstrated the involvement of CXCL1 in the progression of uterine cervical cancer (UCC), which is the fourth leading cause of cancer-related death in women." (PMID 40455858, 2025). "Cancer cells expressed multiple SASP-associated CC (e.g., CCL20) and CXC (e.g., CXCL1, CXCL8, CXCL16) chemokines, which have been shown to be induced by radiotherapy in preclinical models." (PMID 40811032, 2025). "Cancer cells have high expression of CXCR2, so CXCL1 will bind with high affinity to its receptor on the membrane of cancer cells." (PMID 40427171, 2025). "Although the role of CXCL1 in cancer progression is well documented, its impact on cancer therapy has received relatively little attention." (PMID 40427171, 2025). "In the VPP cancers, significant increases were observed in CXCL1, CXCL2, GZMB, IL6, CCL13, and CCL19, among others." (PMID 40361362, 2025). "BCAM-induced proteins, previously reported to drive EMT and associated processes such as cell migration in various cancers, include AREG, CXCL1, CXCL10, EDN1, FGF2, TGFβ1 and VEGFB." (PMID 40082910, 2025). "The discussion focuses on CXCL1-mediated therapy resistance and its contribution to the adverse effects of cancer treatment." (PMID 40427171, 2025). "This review aims to address this gap and highlight the potential of CXCL1 as a therapeutic target in combination with standard cancer treatments." (PMID 40427171, 2025). "CXCL1 levels are frequently elevated in tumors compared to healthy tissue, where they play a key role in promoting cancer cell migration, angiogenesis, and neutrophil recruitment." (PMID 40427171, 2025). "CXCL1 further contributes to immune evasion by upregulating PD-L1 expression on cancer cells, thereby inhibiting cytotoxic lymphocyte activity." (PMID 40427171, 2025). "CXCL1 is one of the most abundant chemokines secreted by TAMs and contributes to cancer growth and metastasis." (PMID 41255573, 2025). "Serum levels of IL-6, IL-8, and GROα/CXCL1 progressively increased with advancing inflammation-to-cancer progression in rats, whereas salivary expression peaks occurred during the inflammatory phase." (PMID 41415031, 2025). "While extensive studies have explored the general involvement of chemokines in cancer development, a comprehensive understanding of the specific role of CXCL1, also known as MGSA or GRO-α, remains elusive." (PMID 39767561, 2024). "We look at how CXCL1 affects cancer cells, including their proliferation, migration, EMT, and metastasis." (PMID 38673949, 2024). "In CRC, Snail-expressing cancer-associated fibroblasts (CAFs) showed different cytokines secretion profiles including CCL1, CCL7, and CXCL1 when compared to normal fibroblasts affecting CRC cell migration." (PMID 38935747, 2024). "Cancer cell production of CXCL1 was found to induce CD8+ T cell exhaustion through the recruitment of polymorphonuclear (PMN)-MDSCs in gastric cancer." (PMID 39409924, 2024). "Patients with this cancer have elevated levels of CXCL1 in their blood and after bone marrow transplantation, CXCL1 levels in the blood return to normal." (PMID 38673949, 2024). "CXCL1 was reported to induce visfatin secretion by cancer cells through a positive feedback loop, thereby maintaining M2 TAM polarization." (PMID 39044824, 2024). "Immunofluorescence assays demonstrated that, compared with that in the UC cohort (P<0.001) and control group (P<0.0001), CXCL1 expression in cancer patients was greater and markedly upregulated." (PMID 39582536, 2024).